RNU7-105P (RNA, U7 small nuclear 105 pseudogene)
Gene: Small nuclear RNA gene on chromosome 11 (72,621,766 to 72,621,827, forward strand). Ensembl gene ENSG00000251919.
Homologues: Orthologues: macaque U7 (95% identical), rabbit U7 (77% identical). Paralogues in human: RNU7-67P (84% identical), RNU7-167P (82% identical), RNU7-175P (82% identical), RNU7-60P (82% identical), RNU7-11P (81% identical), RNU7-137P (81% identical), RNU7-35P (81% identical), RNU7-7P (81% identical), RNU7-113P (79% identical), RNU7-141P (79% identical), RNU7-171P (79% identical), RNU7-22P (79% identical), and 141 more.